H2AC1 (H2A clustered histone 1)
Description:
Core component of nucleosome. Nucleosomes wrap and compact DNA into chromatin, limiting DNA accessibility to the cellular machineries which require DNA as a template. Histones thereby play a central role in transcription regulation, DNA repair, DNA replication and chromosomal stability. DNA accessibility is regulated via a complex set of post-translational modifications of histones, also called histone code, and nucleosome remodeling.
Synonyms: H2AFR; HIST1H2AA; bA317E16.2; H2AA; HISTH2AA; TH2A
Tractability: PROTAC: UniProt records ubiquitination sites on it; ubiquitination databases record sites on it.
Gene: Protein-coding gene on chromosome 6 (25,723,397 to 25,726,562, reverse strand). Ensembl gene ENSG00000164508.
Subcellular location: Nucleus; Chromosome
Subcellular location (Human Protein Atlas): Nucleoplasm
Pathways (Reactome):
Chromatin organization: HATs acetylate histones; HDACs deacetylate histones; RMTs methylate histone arginines
Disease: Dengue Virus-Host Interactions; HCMV Early Events; HCMV Late Events
Metabolism of proteins: Metalloprotease DUBs; UCH proteinases; Ub-specific processing proteases
Gene Ontology:
Molecular function: structural constituent of chromatin; DNA binding; protein heterodimerization activity
Biological process: heterochromatin formation
Cellular component: chromosome, telomeric region; extracellular exosome; nucleoplasm; nucleus; nucleosome; chromosome
Genetic constraint (gnomAD): Loss-of-function variants: 2 observed, 3.17 expected, observed/expected ratio (o/e) 0.63, 90% interval 0.25 to 1.7. That is too few expected variants to judge how well the gene tolerates losing a copy. Missense variants: 218 observed, 182.5 expected, observed/expected ratio (o/e) 1.19, 90% interval 1.07 to 1.34. Synonymous variants: 145 observed, 72.99 expected, observed/expected ratio (o/e) 1.99, 90% interval 1.69 to 1.99.
Homologues: Orthologues: chimpanzee H2AC1 (100% identical), macaque H2AC1 (99% identical), pig H2AC1 (98% identical), dog H2AC1 (94% identical), rabbit H2AC1 (92% identical), rat H2ac1 (91% identical), mouse H2ac1 (86% identical), Drosophila melanogaster His2A:CG31618 (83% identical), Drosophila melanogaster His2A:CG33808 (83% identical), Drosophila melanogaster His2A:CG33814 (83% identical), Drosophila melanogaster His2A:CG33817 (83% identical), Drosophila melanogaster His2A:CG33820 (83% identical), and 16 more. Paralogues in human: H2AC20 (90% identical), H2AC21 (90% identical), H2AC6 (90% identical), H2AJ (90% identical), H2AC11 (89% identical), H2AC13 (89% identical), H2AC15 (89% identical), H2AC16 (89% identical), H2AC17 (89% identical), H2AC18 (89% identical), H2AC19 (89% identical), H2AC25 (89% identical), and 15 more.
Diseases named in the same sentence as H2AC1 in open-access papers:
H2AC1 is named in the same sentence as 3 diseases in open-access papers, as found by Europe PMC text mining. Sharing a sentence is not in itself a finding about the gene and the disease.
H2AC1 shares sentences with these, for which no sentence is quoted: infertile (2 papers); male infertility (1); preeclampsia (1).